COL12A1 (collagen type XII alpha 1 chain)
Diseases named in the same sentence as COL12A1 in open-access papers (continued):
Sharing a sentence is not in itself a finding about the gene and the disease.
overlap syndrome (1 paper, 2025). "Both recessive and dominant mutational mechanisms in COL12A1 cause an emerging overlap syndrome involving muscle and connective tissue." (PMID 39923201, 2025).
renal cell carcinoma (1 paper, 2017). "Reportedly, in renal cell carcinoma, expression of collagen genes are associated with poor prognosis in several tumor types and COL12A1 has been detected to be highly expressed in subtype three tumors." (PMID 27802793, 2017).
sarcopenia (1 paper, 2024). Progressive decline in muscle mass due to aging which results in decreased functional capacity of muscles. "DCN, FSTL1, and COL12A1 are new candidate biomarkers for the comorbidity of SCI and sarcopenia." (PMID 39281413, 2024).
scoliosis (1 paper, 2025). A congenital or acquired spinal deformity characterized by lateral curvature of the spine. "Recently, a homozygous COL12A1 splice variant was identified in a patient with congenital hypotonia, weakness, joint laxity, and progressive scoliosis who was able to achieve independent ambulation and who did not report physical limitations in childhood." (PMID 39923201, 2025). "Recently, a single patient with a homozygous COL12A1 splice site variant was identified, presenting with congenital onset hypotonia and weakness, delayed motor milestones, progressive scoliosis, who nevertheless reported no physical limitations at age 47 years." (PMID 39923201, 2025).
Sepsis (1 paper, 2025). Sepsis is defined as life-threatening organ dysfunction caused by a dysregulated host response to infection. "Key genes identified among these, such as FARSA, SVIL, LAMP2, and COL12A1, were found to be influenced by exercise in both burns and sepsis, suggesting their potential roles in exercise-mediated recovery processes." (PMID 40028316, 2025).
serous ovarian cancer (1 paper, 2025). "Analyses of the ROC database also showed increased COL12A1 expression in serous ovarian cancer patients who did not respond to platinum and taxane chemotherapy." (PMID 40565351, 2025).
serous ovarian tumors (1 paper, 2025). "COL12A1, PLEC, and SLC4A1 expression levels were significantly increased in serous ovarian tumors (grade 3) that did not respond to platinum and taxane chemotherapy compared to responders after 6 months of treatment." (PMID 40565351, 2025).
thyroid tumor (1 paper, 2023). A benign or malignant neoplasm affecting the thyroid gland. "Among the identified hub genes, AEBP1, CD34, COL12A1, ITGA2B, THBS2, and TPO exhibit lower expression levels in thyroid tumors." (PMID 37795451, 2023).
tubulointerstitial nephritis (1 paper, 2020). "Notably, the mix of ADAMTS5-affected matrix proteins was enriched in basement-membrane components including laminins (LAMA/LAMB/LAMC), collagen-6 (COL6A1/A2), collagen-12 (COL12A1), AGRN, nidogen-1 (NID1), and TINAG (tubulointerstitial nephritis Ag)." (PMID 32917786, 2020).
tumor (60 papers, 2009 to 2026). "Elevated COL12A1 expression was linked to increased tumor stiffness and changes in fiber structure, which were reversed with COL12A1 knockdown." (PMID 39716322, 2024). "Higher expression of COL12A1 was associated with tumor progression and worse survival in iCCA patients." (PMID 36694230, 2023). "Nevertheless, an experimental investigation will help understand the direction of the association of COL12A1 with tumor progression." (PMID 35407556, 2022). "Recently, some studies have reported that COL12A1 was associated with the tumor invasion, migration and metastasis, the mechanism in DR has not been reported." (PMID 34233716, 2021). "In this context, MSCMel were found to increase tumor collagen deposition and to modulate molecules primarily associated with collagen folding, such as COL1A2 and COL12A1, suggesting a potential link between these molecular changes and collagen-mediated tumor growth inhibition." (PMID 40083939, 2025). "The other four candidate genes, such as COL12A1, whose upregulation plays a critical role in tumor progression, may also be linked to this racial inequality." (PMID 39445291, 2024). "There were significant associations between these genes and GC tumor stage, except for COL12A1." (PMID 37723519, 2023). "The key factor that caused the COL12A1-induced tumor growth needs further exploration." (PMID 36900272, 2023). "Furthermore, the heightened levels of COL12A1 might also be associated with the activation of specific signaling pathways that promote tumor survival and resistance to therapy." (PMID 40216311, 2025). "Even though they exhibited consistent tumor-normal dysregulation, five genes (COL12A1, CTSB, PLOD1, SPP1, and SULF1) were excluded from the final candidate list as they did not satisfy the meta-analysis criteria and exhibited loss of prognostic significance." (PMID 41451347, 2025). "This increased expression of COL12A1 can positively correlate with tumor invasiveness, metastasis, and a lower overall survival rate." (PMID 38761291, 2024). "In an epigenetic study by Tang and co-workers on intrahepatic CCA, the collagen type XII alpha 1 chain (COL12A1) was identified as a specific biomarker for enrichment in the epithelial–mesenchymal transition pathway and advanced tumor stage." (PMID 38398194, 2024). "The expression of the epithelial transcript marker EPCAM coincided with the expression of COL18A1, TNC and COL12A1 gene transcripts in the tumor clusters." (PMID 39239354, 2024). "The in vivo tumor growth and COL12A1 expression were alleviated by the treatment with the miR-424-5p agonist." (PMID 38398194, 2024). "COL12A1 is recognized to be the desmoplastic biomarker in the differentiation of myofibroblasts within GC, indicating the relation between COL12A1 overexpression and tumor malignancy." (PMID 37700383, 2023). "The Oncomine online tool indicated a higher COL12A1 expression in tumor tissues than that in normal tissues." (PMID 36900272, 2023). "In vivo, JYQHD suppressed xenograft tumor growth in GC, while COL12A1 overexpression promoted xenograft tumor growth and attenuated the anti-tumor effect of JYQHD." (PMID 37700383, 2023). "In colony-forming assays, COL12A1 knockout inhibited tumor cells growth by attenuating colony-forming ability of iCCA cells." (PMID 36694230, 2023). "The expression of COL12A1 was significantly higher in CAF than in tumor cells as evidenced using qPCR." (PMID 36900272, 2023). "In further studies, we need to investigate which part of CAFs expressed COL12A1, and thus plays an important role in tumor growth." (PMID 36900272, 2023). "We also found significantly upregulated myCAF markers in gal 4–KD tumor CAFs, including Col12a1, Col8a1, Thbs2, and Igfbp3." (PMID 36478037, 2023). "COL12A1 co-expression networks were studied using the TCGA database to verify the potential function of COL12A1 in tumor tissues." (PMID 36900272, 2023).
tumor (continued). "Based on the results from enrichment analyses and the marked collagen-rich tumor microenvironment in iCCA, we subsequently investigated the role of COL12A1 in iCCA." (PMID 36694230, 2023). "The TCGA and GETx datasets indicated that COL1A1, COL3A1, COL5A2, COL8A1, COL10A1, and COL12A1 genes were expressed much higher in tumor tissues than in the normal ones." (PMID 36900272, 2023). "Subsequent clinicopathological analysis showed that elevated COL12A1 expression was positively correlated with tumor invasiveness, metastasis and advanced clinical stage." (PMID 37700383, 2023). "COL12A1, a member of the major collagen family of Fibril-Associated Collagens (FACIT) collagens, assumes a key role in tumor growth." (PMID 36900272, 2023). "Collagen type XII alpha 1 chain (COL12A1), encoded by chromosome 6q12‐q13, is a typical collagen‐building molecule involved in collagen cross‐linking in the tumor microenvironment." (PMID 37506150, 2023). "CPTAC and HPA indicated that the protein level of COL12A1 was significantly higher in tumor tissues than in normal tissues." (PMID 36900272, 2023). "Consistent with those within the in-vitro experiments, knockdown of COL12A1 in GC cells reduced the tumor mass growth and decreased the expression of GPX4 and SLC7A11 in xenograft models." (PMID 37700383, 2023). "On the whole, JYQHD inhibited the growth of xenograft tumor via COL12A1-mediated ferroptosis in GC cells." (PMID 37700383, 2023). "Collagen XII (COL12A1) demonstrated highly significant up-regulation in tumours at all stages of development compared to healthy controls." (PMID 35933466, 2022). "More importantly, we found that METTL3 regulated tumor progression by COL12A1-mediated MAPK signaling pathway." (PMID 35399719, 2022). "Genes in the high expression groups, namely, COL1A1, COL4A1, COL12A1, and PDGFRB, were all enriched in the MAPK and PI3K–Akt signaling pathways, which are closely associated with tumor cell proliferation, invasion, and cell cycle." (PMID 35111208, 2021). "Our results showed that as increased in tumor stage and the node metastasis status, the expression levels of COL12A1 promoter methylation decreased (Stage 1 > Stage 2 > Stage 3 > Stage 4; N0 > N1 or N2) (P < .05)." (PMID 32356618, 2020). "Our experiments well clarified a reciprocal positive regulation between IDO1 and COL12A1 to promote tumor metastasis, which was mediated by IDO1 metabolite kynurenine and integrin β1." (PMID 31315643, 2019). "In addition to the shared genes, we also find several genes specific to each region, e.g., COL12A1 in normal and tumor regions (weighted connectivity degrees: 0.54 for tumor; 0.76 for normal)." (PMID 39954675, 2025). "In particular, COL12A1, a critical regulator of tumor matrix organization, was more abundant in tamoxifen-resistant patients in both the EMC and NKI-AVL + RUMC cohorts, with average log2 fold changes of 0.86 (FDR = 1.36 × 10−22) and 0.74 (FDR = 2.07 × 10−7), respectively." (PMID 38632081, 2024). "Recently, COL12A1 has attracted increasing attention in tumor studies." (PMID 37700383, 2023). "Simultaneously, ECM organization, blood vessel development, and regulation of cell-substrate adhesion were enriched in the COL12A1+ fibroblasts, suggesting that they may contribute to tumor invasion." (PMID 37430270, 2023). "Therefore, using bioinformatic analysis and experimental verification, we further explored the source of COL12A1 and investigated the mechanism of its involvement in tumor genesis and development." (PMID 36900272, 2023). "In subcutaneous xenograft models, COL12A1 knockout inhibited tumor growth and proliferation." (PMID 36694230, 2023). "However, the expression of methylated COL12A1 expression was much higher in tumor tissue than in normal tissue in the pancreas." (PMID 36900272, 2023).
tumor (continued). "Of these, COL12A1 was significantly upregulated in clinical iCCA tissue samples and correlated with epithelial–mesenchymal transition gene set enrichment score and advanced tumor stage in clinical iCCA." (PMID 36694230, 2023). "In addition, aggressive clinical features such as advanced tumor stage, positive lymph node status and distant metastasis were observed in patients with COL12A1 overexpression." (PMID 35407556, 2022). "Overexpression of miR-1180-3p may be a tumor suppressor, which inhibits cell growth and mobility but induces cell apoptosis by targeting COL12A1." (PMID 34723759, 2021). "Thus, the normal collagen matrix could be decreased and concurrently replaced by tumor-specific types of collagens (i.e., COL12A1 and COL11A1) in tumor tissues." (PMID 40032993, 2025). "Moreover, the observation of COL12A1 wild type peptides in both the class I and II immunopeptidomes of EN‐181‐11 indicate that this protein is presented in both antigen processing pathways by this tumour." (PMID 36111495, 2023). "Furthermore, this study investigated whether JYQHD exerts its anti-tumor effect through regulating the ferroptosis pathway by targeting COL12A1 in GC cells." (PMID 37700383, 2023). "Simultaneously, COL12A1 could promote tumor cell growth in a paracrine manner." (PMID 36900272, 2023). "A comparison of these with the 683 KPTN tumor–upregulated genes revealed 130 consistently upregulated genes, including ECM components (COL4A1, COL4A2, COL12A1, VCAN, etc.)and YAP targets (ANKRD1, AXL, CYR61, F3)." (PMID 41480763, 2026). "COL12A1 and THBS2 showed enriched expression in tumor tissue section and hyaluronan and proteoglycan link protein 1 (HAPLN1) showed enriched expression in NAT tissue section." (PMID 40032993, 2025). "Based on a previous assay, tumor xenograft assay indicated that JYQHD effectively inhibited GC growth in vivo, while overexpression of COL12A1 counteracted the anticancer effect of JYQHD, and the tumor mass increased significantly compared with JYQHD group." (PMID 37700383, 2023). "COL12A1+ fibroblasts highly expressed MMP2, MMP14, and TGFB1, which are related to tumor cell invasion and ECM degradation." (PMID 37430270, 2023). "KEGG analysis indicated that ADAMTS2, COL12A1, and THBS2 are closely related to ECM, and ECM plays an important role in tumor metastasis and progression." (PMID 35879877, 2023). "PABPC1 and collagen type XII α1 chain (COL12A1) expression in PAAD and their role in tumor prognosis and tumor stage were investigated using The Cancer Genome Atlas database analysis." (PMID 37506150, 2023). "The results revealed that COL1A1, COL4A1, COL12A1, and PDGFRB were all negatively correlated with tumor purity." (PMID 35111208, 2021). "Therefore, miR-1180-3p may act as a tumor-suppressive effect by directly targeting COL12A1." (PMID 34723759, 2021). "Mutations in other collagens, such as COL6A6, COL22A1, COL6A3, COL12A1, and COL14A1, were also noted in a variety of tumor types." (PMID 34584216, 2021). "The expression of COL1A1, COL4A1, COL12A1, and PDGFRB were all negatively correlated with tumor purity." (PMID 35111208, 2021). "According to the expression and survival analysis, three genes (COL12A1, APOL1, and MMP14) were significantly higher in tumor samples when compared with normal controls and their upregulation indicated a poor prognosis." (PMID 33027767, 2020). "By IHC staining, we examined IDO1, COL12A1 and phosphorylation ERK expression in primary tumor of the four groups." (PMID 31315643, 2019). "The gene list they identified shares similarities to gene expressed in our whole tumour sample (ANTXR1, COL12A1, COL5A2, CTHRC1, POSTN)." (PMID 19401702, 2009). "The COL12A1, as a robust independent prognostic marker for GC patients, plays a notable role in the TME, with its expression being significantly increased in GC tissues, correlating with tumor aggressiveness, metastasis, and advanced stages." (PMID 40141097, 2025).
tumor (continued). "The results of this study indicate that PABPC1 may function as a tumor promoter in PAAD, accelerating BXPC3 cell proliferation and metastasis by regulating COL12A1 expression." (PMID 37506150, 2023). "In the current study, the single-cell analysis revealed that COL12A1 was mainly distributed in CAF cells but not in tumor cells and other adjacent cells." (PMID 36900272, 2023). "In addition, the ACTA2, ASPN, PDGFRB, PDPN, COL12A1, EMILIN1, and CDH11 genes were upregulated in CAFs of several tumor types." (PMID 36263012, 2022). "And, hypermethylation of COL12A1 promoter tended to be expressed in lower tumor stage and negative node metastasis." (PMID 32356618, 2020). "Interestingly, increased mRNA expression was already observed in normal tissue of tumor patients compared to healthy donors for THBS2, SPARC, LTBP2 as well as the collagens COL8A1 and COL12A1." (PMID 29176937, 2017). "COL12A1 was mainly expressed in CAFs but not in tumor cells." (PMID 36900272, 2023). "Furthermore, among the identified potential tumor-specific biomarkers, we investigated the expression pattern, clinical relevance, biological function and upstream regulatory mechanism of collagen type XII alpha 1 chain (COL12A1) in iCCA." (PMID 36694230, 2023). "Among the tumor-enriched DEPs within the core matrisome, nearly all are included in the GLY group, with α1 chain of collagen XII (COL12A1) being the only DEP not part of the GLY group." (PMID 40032993, 2025). "Furthermore, COL12A1 was identified in our PCA loading analysis as the strongest ECM component contributing to the second principal component (PC2), which separated late- from early-stage tumours, suggesting it may be strongly associated with tumour progression." (PMID 35933466, 2022). "The other four genes (CPS1, COL12A1, EIF3H, and NBR1) were not upregulated in the tumour region of MSSCC." (PMID 21847129, 2011). "However, the exact mechanism of how COL12A1 effect CAF transformation as well as which subtype CAF was changed and induced tumor growth still not fully elucidated." (PMID 36900272, 2023).